TSPO (translocator protein)
Diseases named in the same sentence as TSPO in open-access papers (continued):
Sharing a sentence is not in itself a finding about the gene and the disease.
neurological disorders (37 papers, 2012 to 2026). "Accordingly, TSPO is regarded as an interesting pharmacological target for diagnostic imaging and anti-inflammatory, neuroprotective drug design for the treatment of neurological disorders." (PMID 39329756, 2024). "In this context, the translocator protein (TSPO) has been proposed as potential macrophage-associated target mainly for imaging microglia/macrophages that play an essential role in neurological disorders." (PMID 32916949, 2020). "Positron emission tomography (PET) radioligands targeting the human translocator membrane protein (TSPO) are broadly used for the investigations of neuroinflammatory conditions associated with neurological disorders." (PMID 30200318, 2018). "This idea aligns with a study from Milenkovic and colleagues, where they examined the two most frequently occurring missense mutations of TSPO (A147T, R162H), which were linked to reduced function and possible neurological disorders, and found that they decreased the half-life of the protein by 25%." (PMID 41019077, 2025). "It has long been recognized that TSPO expression is associated with neurological disorders." (PMID 32252470, 2020). "[11C]PK11195 is a PET radiotracer specifically targeting the translocator protein 18 kDa (TSPO) and is widely used to investigate brain inflammation in relation to various neurological disorders and notably brain ischemia." (PMID 37996697, 2024). "In this context, TSPO imaging can be useful in the differential diagnosis of neurological disorders according to the amount of TSPO expression and its distribution pattern in the brain." (PMID 36980337, 2023). "Previously, animal models of neurological disease using intraperitoneal injections elicit robust neuroimmunogenic responses, such as LPS and kainic acid, have demonstrated diminished TSPO radiotracer parent fraction levels." (PMID 36231041, 2022). "TSPO is involved in cell proliferation and steroid hormone synthesis, and TSPO activation is reported to be beneficial for several kinds of neurological diseases, such as inflammatory and neuropathic pain." (PMID 34248642, 2021). "Here, we provide an exhaustive overview of the recent literature on the TSPO-PET imaging (i) in the search and development of new TSPO tracers and (ii) in the understanding of acute and chronic neuroinflammation in animal models of neurological disorders." (PMID 34245328, 2021). "Assessment of microglial activation in neurodegenerative conditions can be performed through neuroimaging of the 18 kDa translocator protein (TSPO) using selective TSPO radioligands which allow the exploration of microgliosis in neurological disorders." (PMID 34203263, 2021). "Over the past decades, the translocator protein 18 kDa (TSPO), present on the mitochondrial membrane of microglial cells, has been used as an in vivo marker of neuroinflammation in several neurological disorders including MS." (PMID 31705174, 2020). "The use of TSPO as a biomarker for activated microglia in neurological disease with PET imaging has increased in popularity in recent years." (PMID 31479168, 2020). "Translocator protein 18 kDa (TSPO) has been used as a biomarker of brain injury and inflammation in various neurological diseases." (PMID 30034558, 2018). "The pathophysiologic involvement of TSPO in PSIDs is well-documented especially in cardiovascular conditions at the opposite of microglial activation in neurologic disorders which remains controversial." (PMID 29114179, 2017). "Some studies focused on testing anti-inflammatory drugs in neurological disorders adopted TSPO-PET imaging to assess pre- and post-treatment changes in brain inflammatory patterns." (PMID 28475165, 2017). "Both microglia and macrophages undergo “activation” in response to neuronal injury in a variety of neurological disorders and TSPO expression is highly upregulated in both cell types." (PMID 27154521, 2016).
neurological disorders (continued). "TSPO drug ligands are under investigation in the clinic for treatment of psychiatric and neurologic disorders." (PMID 26925573, 2016). "Activation of TSPO is beneficial for several kinds of neurological diseases by promoting neurosteroid synthesis." (PMID 25889665, 2015). "Increased TSPO expression is observed in neurological disorders, such as traumatic brain injury and inflammation." (PMID 25889665, 2015). "Assessment of microglial activation can be performed in vivo in ALS patients through neuroimaging of the 18 kDa translocator protein (TSPO) using selective TSPO radioligands which allow the exploration of microglia in neurological disorders." (PMID 23300829, 2012). "Studies using TSPO PET in other neurological diseases have shown varying results." (PMID 40662329, 2025). "Ongoing research aims to optimize TSPO tracers enhancing the credibility of neuroinflammation assessments through PET imaging but the development of alternative inflammatory tracers is of enormous importance for future studies in neurological disorders." (PMID 38745337, 2024). "Moreover, it has been observed how TSPO expression can differ between PD and different neurological disorders in terms of distribution volume and patterns." (PMID 36980337, 2023). "Nonetheless, the differences in results regarding TSPO PET signals of first and second generations of tracers measured in patients with neurological disorders versus healthy controls indicate that we still have to understand more regarding TSPO characteristics." (PMID 32252470, 2020). "Since the inflammatory phenotype of glial cells is critical to their role in neurological disease, these findings may enhance the utility and application of TSPO imaging." (PMID 31479168, 2020). "Over the past decade, TSPO-PET and DCE-MRI have demonstrated increased clinical utility for tracking inflammatory mechanisms contributing to neurological disease onset and progression." (PMID 41257741, 2025). "Last, using translocator protein positron emission tomography (TSPO-PET) imaging, we show that the skull bone marrow reflects inflammatory brain responses with a disease-specific spatial distribution in patients with various neurological disorders." (PMID 37562402, 2023). "However, recent studies with TSPO have highlighted that increased TSPO expression in neurological disorders does not necessarily indicate upregulation of TSPO, instead, it’s associated with increased glial density resulting in higher TSPO signals." (PMID 37891168, 2023).
brain diseases (16 papers, 2017 to 2025). "It was only in the mid- to late 1990s, using animal models of brain diseases that an increased level of TSPO/PBR was proven to be associated with microglial activation." (PMID 34245328, 2021). "In a recent review by us, we discussed the potential involvement of a mitochondrial protein (the 18 kDa Translocator Protein; TSPO ) in brain disorders." (PMID 32380741, 2020). "TSPO PET imaging with first-generation ligands showed promise in both the rhesus macaque models of HIV brain disease and in humans." (PMID 32943056, 2020). "The inflammatory reaction promotes a dramatic increase of a mitochondrial transmembrane protein, the translocator protein (TSPO), considered as the hallmark of neuroinflammation in brain diseases." (PMID 29177913, 2017). "TSPO is an outer mitochondrial membrane protein, and elevations of TSPO expression have been consistently observed in microglial and macrophage populations during brain disease." (PMID 33515765, 2021). "We show that TSPO expression increases in activated microglia in mouse brain disease models but does not change in a non-human primate disease model or in common neurodegenerative and neuroinflammatory human diseases." (PMID 37640701, 2023). "Given the extensive evidence that TSPO is upregulated in neuroinflammation, there is a significant clinical interest in optimising TSPO PET imaging to better capture various facets of inflammation in human brain disorders." (PMID 37032328, 2023). "One of the TSPO-PET imaging method’s drawbacks is that there are still few clinical studies and in-depth investigations into the cell types accountable for the TSPO response in several brain diseases." (PMID 36432736, 2022). "In brain diseases, in vivo positron emission tomography (PET) exploration of inflammation has matured over the last 20 years, through the development of radiopharmaceuticals targeting the translocator protein-18 kDa (TSPO) as molecular biomarkers of activated microglia." (PMID 29114179, 2017). "Relative to the increase in the TSPO expression that occurs slightly later during neuroinflammation in a proinflammatory fashion, CB2 activation is considered to relate to the neuroprotective responses that occurs predominantly at an early stage of brain disorders." (PMID 28356120, 2017).
infection (16 papers, 2016 to 2026). The state of being infected such as from the introduction of a foreign agent such as serum, vaccine, antigenic substance or organism. "Moreover, infection with Jan-E EHV-1 was followed by a more than two-fold increase in expression of the gene encoding Translocator Protein (Tspo), which plays an important role in the transport of cholesterol to mitochondria and is involved in their metabolism." (PMID 36014997, 2022). "Only the myeloid subset of immune cells—specifically granulocytes, monocytes, and microglia, exhibited higher TSPO expression in ZIKV disease relative to pre-infection." (PMID 36348095, 2023). "This supports the twofold increased ex vivo [18F]FEPPA blood activity at late disease relative to pre-infection, and indicates that immune cells represent a true TSPO target for radioligand binding in the blood." (PMID 36348095, 2023). "Aside from microglia, monocytes also exhibited elevated TSPO expression at late disease, which was 2.9-fold higher than pre-infection (p = 0.02)." (PMID 36348095, 2023). "No increase in tracer binding to brain tissue was observed at mid ZIKV disease relative to pre-infection, consistent with TSPO immunostaining findings." (PMID 36348095, 2023). "This study investigates ZIKV-associated changes in adult brain TSPO expression, evaluates the effectiveness of TSPO radioligands in detecting TSPO expression, and identifies cells that drive brain TSPO expression in a mouse infection model." (PMID 36348095, 2023). "We chose two different time points post-infection to demonstrate disease-dependent increase in binding of TSPO radioligands [3H]PK11195 and [18F]FEPPA using tissue autoradiography and ex vivo tissue biodistribution studies." (PMID 36348095, 2023). "TSPO PET revealed an increased tracer uptake throughout the brain of all infected animals already from the first scan obtained post-infection (day 2), which increased to approximately twofold until day 30 pi." (PMID 37516868, 2023). "This trend is reproduced in various micro-dissected brain regions, where TSPO expression by immune cells at late disease increased by 1.3- to 3.0-fold compared to pre-infection, and the highest increase was recorded in the hippocampus and cerebral cortex." (PMID 36348095, 2023). "To explore the role of TSPO in microglia, we isolated primary microglial cells from WT and TSPO−/− mice and silenced TSPO in BV2 cells by infection with lentivirus containing TSPO shRNA." (PMID 32695005, 2020). "TSPO expression in microglia from whole brains was 3.9-fold higher than pre-infection (p = 0.006)." (PMID 36348095, 2023). "Of the 6 macaques, 3 underwent additional TSPO-targeting [18F]F-DPA714 PET/CT investigations at baseline and at days 2, 9, 23, and 51 after infection." (PMID 40876955, 2026). "The enhanced TSPO PET signal that was observed in SARS-CoV-2 infected animals, during the course of infection, implies that the glial cell density is affected by the virus, and that the brain generates a lasting innate immune response." (PMID 37516868, 2023). "Compared to pre-infection, CD45+ cell TSPO expression at mid and late ZIKV disease were 1.7-fold (p = 0.03) and 1.9-fold (p = 0.02) higher, respectively." (PMID 36348095, 2023). "In response to infection, in male mice, the TACC2, BUB1B, ATP5MC3, and MYO1E, and in female mice, the CAP1, MRPL2, COX5A, KLHL21, PDIA6, TSPO, and USP14 had direct interaction with TP-53." (PMID 35844510, 2022). "Altogether, the TSPO expression profile and immune cell landscape in ZIKV brains provide strong support of TSPO as a biologically relevant imaging target for ZIKV neuroinflammation in our infection model." (PMID 36348095, 2023). "Also, the mouse study reported increased TSPO signals post infection in anatomically unaffected lung tissue, which was not detectable in our TB study in NHP." (PMID 41120776, 2025).
infection (continued). "For example, in an infection-mediated neurodevelopmental mouse model of schizophrenia, behavioural abnormalities were associated with raised cytokine concentrations in the PFC but with reduced prefrontal TSPO concentrations with no microglial activation." (PMID 32606376, 2021). "However, the role of TSPO in infection-induced inflammatory changes has not yet been explored." (PMID 31901235, 2020). "This enhanced sensitivity of TSPO, however, was not apparent from our NHP data, which may be explained by model specific characteristics (e.g. TSPO regulation, body size or experimental infection dose), or using SPECT versus PET." (PMID 41120776, 2025).
central nervous system diseases (7 papers, 2017 to 2025). "This review describes the cellular sources and functions of TSPO in animal models of disease and human studies, in health, and in central nervous system diseases." (PMID 33433698, 2021). "PET imaging of TSPO has widely grown over the last two decades to evaluate the role of neuroinflammation in the central nervous system diseases and to assess novel anti-inflammatory therapeutic strategies." (PMID 29177913, 2017). "Higher TSPO expression in activated microglia during neuroinflammation provides a novel target for radiotracers in PET imaging in order to identify neuroinflammation in various central nervous system diseases." (PMID 34483820, 2021). "On the same immobilized vesicles, we explored also the expression of Translocator Protein (TSPO) receptor which is known to be a marker of neuroinflammation, playing an important role in glial activation and neuronal cell death in many central nervous system diseases and injuries." (PMID 37175644, 2023).
cardiac diseases (5 papers, 2019 to 2025). "The role of TSPO in the heart has not been completely understood; however, it is known that the protein is implicated in the pathophysiology of cardiac diseases and its ligands improve heart function, which permits consideration of TSPO as a potential target for therapy of cardiovascular diseases." (PMID 31766490, 2019).
inflammation (5 papers, 2017 to 2026). Aberrant reaction of the microcirculation characterized by movement of fluid and leukocytes from the blood into extravascular tissues. "LVV is marked by a local intramural chronic granulomatous inflammation of the aortal vessel wall and that of its main branches, which is characterized by the presence of macrophages that highly express TSPO." (PMID 38139248, 2023). "The translocator protein (TSPO) has been implicated in mitochondrial transmembrane cholesterol transport, brain inflammation, and other mitochondrial functions." (PMID 35522669, 2022).
benign tumors (3 papers, 2017 to 2025). "TSPO is described as an outer mitochondrial membrane protein and its activity is associated with mitochondrial permeability transition pore (mPTP) opening as well as increased oxidative stress in the ischemic heart." (PMID 33799869, 2021). "Consistent with our previous studies, TSPO expression was lower in MPNST than in benign tumors." (PMID 40842566, 2025).
CNS tumors (3 papers, 2016 to 2025). "Genotyping for this polymorphism in patients with CNS tumours would therefore be required before enrolment in TSPO imaging studies." (PMID 27077069, 2016). "Collectively, these emerging tracers targeting GRPR, TSPO, and integrin-αvβ3 demonstrate feasibility for receptor-based imaging in pediatric CNS tumors." (PMID 40563556, 2025). "These agents target distinct molecular markers, such as gastrin-releasing peptide receptor (GRPR), translocator protein (TSPO), and integrin-αvβ3, that have been shown to be overexpressed in various CNS tumors." (PMID 40563556, 2025). "An effort should be made to clarify epigenetic regulation of TSPO gene in CNS tumour entities before embarking on TSPO imaging studies." (PMID 27077069, 2016). "Research should address the understanding the functions of TSPO in human CNS tumours and the evaluation of the extent of expression in the various entities." (PMID 27077069, 2016). "This review aims to appraise the literature and discuss the advantages and challenges of investigating the TSPO as a target of molecular imaging for CNS tumours." (PMID 27077069, 2016). "It is our opinion that molecular imaging can play a role in developing personalised treatment strategies for patients with CNS tumours by exploiting the substantially increased levels of TSPO in high-grade gliomas compared to the normal brain." (PMID 27077069, 2016). "Although unrelated to CNS tumours, two studies have provided valuable data to TSPO imaging in neuro-oncology." (PMID 27077069, 2016). "Research on TSPO in CNS tumours is still at its early phase." (PMID 27077069, 2016).
metabolic disease (2 papers, 2021 to 2025). A congenital disorder (due to inherited enzyme abnormality) or acquired (due to failure of a metabolically important organ) disorder resulting from an abnormal metabolic process. "The GSVA findings indicate that the downregulation of the TSPO gene in AD is linked to pathological mechanisms such as inflammatory responses, neurodegeneration, metabolic disorders, and immune abnormalities." (PMID 39919076, 2025).
mitochondrial disease (2 papers, 2020 to 2021). "We describe [11C]PK11195 PET brain imaging of the mitochondrial outer membrane protein TSPO in a group of representative patients with genetically confirmed mitochondrial disease." (PMID 33883237, 2021). "To explore the possibilities of radioligands against the mitochondrial outer membrane translocator protein (TSPO) as biomarkers for mitochondrial disease, we performed brain PET-MRI with [11C]PK11195 in 14 patients with genetically confirmed mitochondrial disease and 33 matched controls." (PMID 33883237, 2021). "However, information on the role of the TSPO in the pathogenesis of mitochondrial diseases remains extremely scarce." (PMID 32722345, 2020). "We found that, on average, in patients with mitochondrial disease, white matter was more likely to show reduced rather than increased TSPO abundance compared to controls." (PMID 33883237, 2021).
neurodevelopmental disorder (2 papers, 2020 to 2024). A behavioral and cognitive disorder with onset during the developmental period that involves impaired or aberrant development of intellectual, motor, or social functions. "PET has already highlighted the activity of microglia in contexts of neurodegeneration, inflammation and neurodevelopmental disorders, as measured using the translocator protein (TSPO) as a target." (PMID 38425429, 2024). "Given that TSPO expression is not only altered merely as a result of microglial activation but could also be an indicator of disease severity and/or progression, TSPO has also been considered for the diagnosis of neurodevelopmental disorders." (PMID 32252470, 2020).
neoplastic disorders (1 paper, 2018). "Expression of TSPO is upregulated in activated microglia in various neuroinflammatory, neurodegenerative, and neoplastic disorders." (PMID 29641545, 2018).
retinopathy (1 paper, 2025). "The antiinflammatory effect of minocycline at the early stage of pericyte-depletion retinopathy was corroborated by the downregulation of CCL2, iNOS, TSPO, and LGALS3 in minocycline-treated APB5 retinas at P10." (PMID 40591415, 2025).